NCF1 (neutrophil cytosolic factor 1)
Diseases named in the same sentence as NCF1 in open-access papers (continued):
Sharing a sentence is not in itself a finding about the gene and the disease.
infection (51 papers, 2011 to 2025). The state of being infected such as from the introduction of a foreign agent such as serum, vaccine, antigenic substance or organism. "The high mortality of Ncf1-/- mice was associated with an abrupt and significant weight loss after infection while the body weight was stable in WT mice." (PMID 29228045, 2017). "Gene therapy using lentiviral vectors to deliver functional NCF1 has shown promise, achieving partial restoration of ROS production in patient-derived neutrophils and a reduction in infection rates in preclinical models." (PMID 40710296, 2025). "The expression of neutrophil cytosolic factor 1 (ncf1), which encodes a subunit of NADPH oxidase, was decreased at 24 hpi with mVenus-PR8 infection." (PMID 38275965, 2024). "A total of 117 cases of infection in the 100 patients were identified (100 associated with CYBB, 10 with CYBA, 3 with NCF1 and 1 with NCF2 mutations), and all had experienced at least 1 infectious episode (IQR 1–3)." (PMID 33168948, 2020). "NCF1-defective mice infected with Mycobacterium marinum demonstrated increased infection loads compared to wild type mice, which also resulted in increased IL1β activity." (PMID 31415633, 2019). "A group of Treg-signature genes (Areg, Arhpag20, Bub1b, Ccl12, Ccr5, Il1r1, Mki67 (Ki67) Ncf1, Nrp2, Tnfrsf9, Tcf19, Uhrf1, and Wnt3) were expressed at higher levels in IFNARfl/fl x Foxp3YFP-Cre mice than WT controls on day 5 Armstrong infection." (PMID 29672594, 2018). "CD28 KO mice display T cell activation defects, and NCF1 (p47phox/NOX2) display a reduced type 1 CD8+ T cell response, leading to impaired control of parasitism and increased susceptibility to infection." (PMID 30559742, 2018). "We found that depletion of IL-1β ameliorated the tissue inflammation in both M. marinum-infected Ncf1-/- and WT mice on day5 after infection." (PMID 29228045, 2017). "Expression of iNOS protein in the lung at 4 weeks post-infection was significantly increased in Ncf1 mutant as compared to wild-type mice." (PMID 25188296, 2014). "The pattern was slightly different for IFN-γ: there were increased in Ncf1 mutant mice at 3 days and 4 weeks post-infection, however Ncf1 rescue mice showed even higher IFN-γ levels 4 weeks post-infection." (PMID 25188296, 2014). "Three days post infection, the increase of TNF levels in Ncf1 mutant lung was massive (3.6-fold compared to wild-type) and also observed at four weeks post-infection." (PMID 25188296, 2014). "Bacterial load in the lung of both the Ncf1 mutant and Ncf1 rescue mice were similar but higher than those in wild-type mice 3 days after infection." (PMID 25188296, 2014). "The general pattern was an increase in pulmonary cytokine and chemokine responses in Ncf1 mutant mice due to the infection which was controlled by Ncf1 rescue mice." (PMID 25188296, 2014). "Interestingly, however, Ncf-1-/- mice had significantly higher fungal burden in the peritoneal cavity but a comparable level in the kidney compared to Ncf-1+/+ mice at 3 h after infection." (PMID 31693704, 2019). "The surviving Ncf1 mutant mice (5 out of 15) were also analyzed at 4 weeks post-infection." (PMID 25188296, 2014). "CCL5 levels were increased in Ncf1 mutant mice three days and 4 weeks after infection." (PMID 25188296, 2014). "In the low-dose infection, we found a similar CFU counts between WT mice and Ncf1-/- mice." (PMID 29228045, 2017). "There is one exception to this: the moderately increased mycobacterial load, which is not reversed by Ncf1 rescue in macrophages and hence was not correlated to the outcome of infection." (PMID 25188296, 2014). "Ncf1 rescue as wild-type mice resisted the infection during the 4 weeks observation and no mortality or no important weight loss was observed." (PMID 25188296, 2014).
infection (continued). "Notably, the levels of activated caspase-1 and released IL-1β in response to LPS and ATP, which activate the NLRP3 inflammasome; dsDNA transfection and infection with F. novicida, both as activators of the AIM2 inflammasome, were reduced following transfection with Ncf1, Ncf2, or Ncf4 siRNAs." (PMID 38886341, 2024). "Three days, but not 4 weeks, post infection, IL-17 lung levels were increased in Ncf1 mutant mice." (PMID 25188296, 2014).
tumor (29 papers, 2011 to 2025). "Studies in NCF1−/− mice suggest that p47phox deficiency modulates immune responses in cancer, potentially affecting tumor progression through altered ROS signaling." (PMID 40710296, 2025). "Tumor metastasis has been found to be closely related to Ncf1 gene polymorphisms that cause a poor ROS response." (PMID 37274231, 2023). "The susceptibility to tumor colonization was restored by the human S100A8 (MRP8) promoter directing a functional Ncf1 expression to granulocytes." (PMID 34257370, 2021). "To study the role of redox regulation of tumor colonization, we introgressed the Ncf1 mutation in mice with the MHC b, q, and r haplotypes on the shared C57BL genome background." (PMID 34257370, 2021). "Our data suggest targeting B-cell specific ROS may be sufficient in regulating B16F10 anti-tumor immunity in NCF1-deficient mice." (PMID 41300507, 2025). "In a recent contribution to The Journal of Pathology, van der Weyden et al2 reported that mice deficient in any of the five NOX2 subunits Cyba, Cybb, Ncf1, Ncf2 or Ncf4 were markedly less prone to develop lung metastases following intravenous injection of several histiotypes of tumor cells." (PMID 30270440, 2019). "In this study, we decided to investigate the contribution of B cell derived NOX2-NCF1-ROS towards B16F10 tumor progression, using a conditional knock-in on our Ncf1*/*mutant stain." (PMID 41300507, 2025). "Mindful that Ncf1*/* mice have stunted tumor progression when compared to B6NQ mice, we extended our disease model from 10 to 21 days to 28 days." (PMID 41300507, 2025). "The pseudotime analysis further validated this trend, showing a significant increase in TGFβ1+ Tregs during the late tumor grade, while NCF1+ Tregs and proliferative Tregs decreased, a pattern opposite to that observed in the early pseudotime grades." (PMID 40891683, 2025). "We observed increased frequencies of Tregs from the lungs of auranofin and TRi-1 treated Ncf1*/* mice vs. controls as well as significantly augmented B16F10 tumor burden." (PMID 41300507, 2025). "Taken together, these results implied that NCF-1-producing tumor cells are resistant to ROS-mediated cytotoxic effects." (PMID 39666242, 2024). "We next examined the effect, in tumor cells, of NCF-1 expression on the intracellular levels of regulators (glutathione synthetase (GSS) and glutathione peroxidase 4 (GPX4)) and a mediator (glutathione (GSH)) of ROS production." (PMID 39666242, 2024). "Natural killer cells and T cells, the major fighters in anti-tumor immune, are prone to apoptosis upon NCF1 acting." (PMID 37065491, 2023). "Differential expression was observed between tumor and normal tissues for NCF1, NCF2, and NCF4 in KIRC data from TCGA." (PMID 34708124, 2021). "MRP8-restricted expression of a functional Ncf1 restored the release of IL-1β from neutrophils and the susceptivity to tumor colonization." (PMID 34257370, 2021). "Recent research published in the Journal of Pathology showed that genetic depletion of any of the NOX2 subunits Cyba, Cybb, Ncf1, Ncf2 and Ncf4 reduced the formation of lung metastases following intravenous injection of murine tumor cells." (PMID 30270440, 2019). "T cells were gated for memory markers (CD62L and CD44) and CD4/CD8 ratio by gating on live singlet CD3+ T cells.The CD4/CD8 T cell ratio was compared between tumor bearing NCF1*/* and NCF1*/+ mice." (PMID 26076008, 2015). "MCA-induced tumors significantly increased the amount of MDSCs present in the spleen in both NCF1*/* and NCF1*/+ mice compared to tumor free wild type mice." (PMID 26076008, 2015). "We found that tumor lines generated in NCF1*/* and NCF1*/+ mice produced similar amounts of free radicals." (PMID 26076008, 2015). "Next we examined the phenotype of the tumor infiltrating T cells in the MCA induced NCF1*/* and NCF1*/+ mice." (PMID 26076008, 2015).
tumor (continued). "The fraction of CD4 T cells secreting IFN-γ was found to be significantly higher (p<0.05) in the spleens of NCF1*/+ mice and showed a similar trend at the tumor site." (PMID 26076008, 2015). "We evaluated the ability of T cells to function and produce IFN-γ, IL-2, IL-4, and IL-17 upon short-term stimulation with PMA and found very few differences in functional T cell capacity between NCF1*/* and NCF1*/+ tumor bearing mice." (PMID 26076008, 2015). "Additionally, NCF1+ Tregs manage oxidative stress responses, protecting tumor cells from oxidative damage." (PMID 40891683, 2025). "Notably, the upregulation of several of these genes, particularly NCF1, HSPB1, PIGT, and PTX3, was associated with poor prognosis, supporting the idea that these genes play a pivotal role in tumor progression and patient survival." (PMID 40656950, 2025). "In mammary tumor models, NCF1−/− may reduce tumor progression through altered NOX activity by affecting MMP-9 and VEGF." (PMID 40710296, 2025). "Notably, these data show auranofin and TRi-1 treated Ncf1*/* mice present with Treg frequencies and tumor burden approaching in similarity to that of control treated wild type mice." (PMID 41300507, 2025). "Consequently, the tumor cells highly expressing NCF-1 obtained coincident accumulation of ROS and reduced glutathione (GSH) with expression of glutathione peroxidase 4 (GPX4), a quencher involved in ferroptosis." (PMID 39666242, 2024). "Our results demonstrated that NCF-1 is found not only in inflammatory cells but also in tumor cells of gastric and pancreatic origins, where the protein appears to play an essential role in the survival of these tumor cells." (PMID 39666242, 2024). "These receptors can recognize sialic acid structures on tumor surfaces, activating downstream Syk-Neutrophil cytosolic factor 1 (P47phox) signaling pathways and the arachidonic acid (AA)-12 and 15-lipoxygenase (HETE)-peroxisome proliferator-activated receptor γ (PPARγ) signaling axis." (PMID 39590166, 2024). "It is reported that NCF1 may positively correlate with pro-tumor M2 macrophages by promoting macrophages differentiating toward M2 macrophages." (PMID 37065491, 2023). "In this study, we show that the Ncf1 mutation protected from tumor colonization, irrespective of the CD68-expressing cell status." (PMID 34257370, 2021). "Moreover, neutrophil depletion by anti-Ly6G antibodies increased tumor colonization in wild type but failed in the Ncf1 mutant mice." (PMID 34257370, 2021). "We observed fewer tumor foci in Ncf1 mutant mice, irrespective of αβT, γδT, B-cell deficiencies, or of a functional Ncf1 expression in CD68-positive monocytes/macrophages." (PMID 34257370, 2021). "In summary, we used naturally mutant mouse models of the Ncf1 gene to screen the cell-type-specific effect of the NOX2 complex deficiency, and then found out that only Ncf1 expression in neutrophils can restore the susceptibility to tumor colonization." (PMID 34257370, 2021). "In addition, NCF1 tumor cell lines were treated with γ radiation at 10 Gy which led to mitotic cell death." (PMID 26076008, 2015). "Using a natural mutation in the Ncf1 gene (encoding a cytosolic component of the NADPH oxidase 2 [NOX2] complex), a group identified that Ncf1 competent neutrophils exhibited functional induction of ROS and IL‐1β signaling, thus promoting lung colonization by tumor cells." (PMID 38062888, 2023). "However, we found that NK cell depletion, by anti-NK1.1 treatments, enhanced tumor metastasis independent of the Ncf1 mutation." (PMID 34257370, 2021). "In vitro RNA interference assays revealed that depletion of NCF-1 induces cell death in both BxPC-3 and HSC-58 cells, indicating that NCF-1 is essential for the survival of such tumor cells." (PMID 39666242, 2024). "Neutrophil cytoplasmic factor 1 (NCF1) belongs to the NADPH oxidase complex and is a cytoplasmic component, which plays a role in tumor growth and metastasis." (PMID 35847888, 2022).
tumor (continued). "As the Ncf1 expression is polymorphic in both humans and experimental animals, and since redox regulation is a key pathophysiologic process, this observation could be of key importance not only to understand the basis of tumor metastasis, but also to improve cancer treatment." (PMID 34257370, 2021). "In order to preliminarily evaluate the role in tumorigenesis, we analyzed the different expression levels for NCF1, NCF2, and NCF4 between tumor and adjacent normal tissues in all TCGA tumors." (PMID 34708124, 2021). "And we further proved that especially NCF1 and NCF4 were significantly correlated with high tumor grade and clinic stage." (PMID 34708124, 2021). "Fifteen in vitro tumor cell lines were generated from tumors extracted from MCA inoculated NCF1*/* and NCF1*/+ mice." (PMID 26076008, 2015). "This suggested that biological producers of H2O2 such as immune cells expressing NCF1/NOX2 may also play a direct role in Treg expansion, impacting anti-tumor immunity." (PMID 41300507, 2025). "This appears to be in disagreement with our findings, where regardless of the NCF1 mutation status, MDSC ́s increased both in the periphery and within the tumor." (PMID 26076008, 2015). "Finally, we isolated the CD15+ cells and CD4/CD8pos T cells at 24 h from APCCs and analyzed the expression of key immune‐suppressive genes of MDSCs (ARG1, NCF1, NCF4, CYBB) which mediate MDSC arginase 1 secretion and NO generation to inhibit T cells within the tumor TME." (PMID 35611994, 2022). "Apart from MAATS1, NCF1, and TRIP12, no other genes were mutated in more than one tumor." (PMID 27494029, 2016). "Similarly, oxidative stress did not vary greatly between NCF1*/* and NCF1*/+ mice in spleen or tumor infiltrating T cells or MDSCs." (PMID 26076008, 2015). "Treatment of either CD33+ or CD11b+ tumor-cell line-induced MDSC with lipopolysaccharide, a known activator of MDSC function, caused further up-regulation of STAT3, C/EBPβ, and HIF1α concurrent with increased expression of ARG-1, iNOS, and NOX2-component NCF1 (data not shown)." (PMID 21658270, 2011). "Interestingly, the expression of NCF4 and NCF1, but not that of NCF2, was significantly downregulated in tumor tissues compared to that in control tissues." (PMID 38886341, 2024).
cancer (19 papers, 2013 to 2025). A tumor composed of atypical neoplastic, often pleomorphic cells that invade other tissues. "The induced immune responses by Ncf1 mutations may on the other hand prevent cancer." (PMID 34257370, 2021). "Normal foveolar epithelia displayed no or very weak staining for NCF-1, which made clear difference in expression level of NCF-1 on cancer cells." (PMID 39666242, 2024). "To address the role of NCF-1 expression in cancer cells, we employed an RNA interference assay using siRNA specific to NCF-1 (siNCF-1) on BxPC-3, HSC-58, and HeLa." (PMID 39666242, 2024). "Metastatic foci of PDACs to lymph nodes retained NCF-1 expression on the cancer cells, which was similar to that seen at the primary sites." (PMID 39666242, 2024). "First, endogenous expression of NCF-1 was examined in patient cancer tissues." (PMID 39666242, 2024). "CYBB, CYBA, NCF1, NCF2, and RAC2 are NADPH oxidase (NOX) subunit genes and are associated with inflammation and fibrosis in multiple organs, such as the liver, lungs, and kidneys, as well as with various types of cancer." (PMID 37109526, 2023). "However, the expression and biological roles of NCF-1 in malignant tumors remain poorly defined." (PMID 39666242, 2024). "NCF-1 has been examined primarily in terms of ROS-production pathways in macrophages and neutrophils; however, the expression of this protein and its biological role in cancer cells remain unclear." (PMID 39666242, 2024). "We found that 30 of these genes which included Nckap1l, Ncf1, Pla2g15, Unc93b1, Lrrc33, Rgs10, Gmfg, Rbm25, C3ar1, Ccdc88b, Fam105a, Gng11, Phc1, Rasa4, Dag1, Tyrobp, Tmsb4x, Cfp, Prkd1, Gp49a, Trem2, C1qc, Lyz2, Igfbp7, Rab30, Cxcl16, Egfl7, Ube2r2, Pltp, and Cfb, showed a relation with cancer." (PMID 32812032, 2020). "High expression of PILRA enhances the effect of antitumor immunotherapy, but its effects vary in different cancers.On the other hand, MYOIF, ILRA2, and NCF1 are considered prognostically unfavorable factors." (PMID 38799454, 2024). "Together, these results indicate that NCF-1 may not be essential for cell survival in all types of cancer, a distinction that may reflect different mechanisms of growth in tumors of distinct etiology." (PMID 39666242, 2024).
kidney disease (4 papers, 2022 to 2025). "Ncf1, encoding a subunit of the NADPH oxidase complex, is involved in neutrophil function, inflammation, and oxidative stress, all of which are critical in kidney disease pathogenesis." (PMID 40305204, 2025).
adenocarcinoma (3 papers, 2018 to 2024). A common cancer characterized by the presence of malignant glandular cells. "We show that basal glands, the hallmark of the WT response, were mostly insignificant in Ncf1 mice, which displayed installed dysplasia, quickly evolving to invasive well-differentiated adenocarcinoma." (PMID 29867918, 2018). "However, we observe an accumulation of β-catenin expressing lymphocytes in the inflammatory foci of the Ncf1 colon near well-differentiated adenocarcinoma." (PMID 29867918, 2018). "Furthermore, after a 21-day resting period we observed lower inflammatory reparation and high-grade dysplasia and invasive well-differentiated adenocarcinoma in the Ncf1 mice while in the WT mice, dysplasia was also prominent without malignant invasion." (PMID 29867918, 2018). "After a 21-day resting period, there was still β-catenin-rich inflammatory infiltration in the Ncf1 mice together with high-grade dysplasia and invasive well-differentiated adenocarcinoma, while in the WT mice, high-grade dysplasia was prominent without malignant invasion and only low inflammation." (PMID 29867918, 2018). "The present study shows that villous/superficial papillary adaptation of the flat mucosa was not relevant to adenocarcinoma morphology and that the inflammation process in Ncf1 colon form a spectrum from acute to the adaptive presence of inflammatory cells." (PMID 29867918, 2018).
bacterial infections (3 papers, 2017 to 2020). "Thus, our results here suggest that melatonin is a functional agent preventing the virulence effect of rVvpM by regulating the spatial distribution of MT2 and NCF-1 to block ROS production during the regulation of bacterial infections." (PMID 31906951, 2020).
inflammation (3 papers, 2014 to 2025). Aberrant reaction of the microcirculation characterized by movement of fluid and leukocytes from the blood into extravascular tissues. "On the contrary, Ncf1 appeared to play only a minor role in IL-25 stimulated lung inflammation." (PMID 34970267, 2021). "Thus, our results indicate that Ncf1 deficiency enhances Th1 response, and thereby deactivates ILC2 lymphocytes, limiting the development of lung inflammation." (PMID 34970267, 2021).
infectious disease (2 papers, 2017 to 2025). A disorder directly resulting from the presence and activity of a microbial, viral, or parasitic agent in humans. "This suggests that the NCF1 Arg90His variant may confer an evolutionary advantage, possibly by offering protection against infectious diseases." (PMID 39917298, 2025).